AR (androgen receptor)
Diseases named in the same sentence as AR in open-access papers (continued):
Sharing a sentence is not in itself a finding about the gene and the disease.
prostate carcinoma (continued). "In addition, androgen-driven AR signaling and associated transcriptional activity have been found to be a focal signaling axis in prostate cancer." (PMID 36837903, 2023). "Further, since binding of PER to androgen receptor (AR) causes the inhibition of AR transcriptional activity, the disruption of circadian rhythm may cause prostate cancer." (PMID 37475884, 2023). "Our hypothesis was that pTEN loss, a common feature in castrate-resistant prostate cancer patients and seen in AR-positive LNCaP and AR-negative PC-3 cells, reduces the influence of resveratrol on maximum synergy in DU145 cells." (PMID 36960209, 2023). "Overall, our findings suggest that YIV-818-A, RA-V, and RA-VII hold promise as potential treatments for prostate cancers with AR, AR-V (AR splice variants) and might be beneficial in enzalutamide-resistant cases with GR overexpression." (PMID 37860121, 2023). "The number of prostate cancer researchers with less than 100 cases limited the ability to study the association with androgen-receptor gene mutation, and the influence of low penetrance gene (such as GST) polymorphism needed hundreds of patients to be recognized." (PMID 36824501, 2023). "Together, these data demonstrate that the loss of methylation-sensitive PP2A heterotrimers from the chromatin upon LCMT1 silencing results in hyperphosphorylation mediated amplified AR-signaling leading to ligand-independent AR addiction, a hallmark of prostate cancer." (PMID 37644036, 2023). "Androgenic hormone-regulated transcriptional activity of androgen receptor (AR) is vital for the normal development and function of the prostate but aberrant AR signaling is a major hallmark and driver of prostate cancer, the second highest cancer of men in the US and worldwide." (PMID 36831540, 2023). "Examples of selectively targeted mutations to therapeutic agents are anti-androgens in the treatment of prostate cancer, where the androgen receptor incurs a mutation to the targeting ligand binding domain, where now the antagonizing drug functions act as agonists." (PMID 36671680, 2023). "AR also exerts pathogenic functions in various cancer types, particularly in prostate cancer." (PMID 36746917, 2023). "In LNCaP95 prostate cancer cells, the Hsp70 inhibitor 1 induced apoptosis and suppressed the expression of the full-length androgen receptor (AR-FL) and of the androgen receptor splice variant 7 (AR-V7), which are associated with castration-resistant prostate cancer (CRPC)." (PMID 36835501, 2023). "However, there were few reports that demonstrated the association of AR antagonists and androgen depletion in prostate cancer with senescence." (PMID 37190127, 2023). "Also, it is obtained that most of the studied genes (TMPRSS2, ERG, ETV5 and AR) are associated with pathways involved in the development of prostate cancer." (PMID 37287057, 2023). "Here, the authors show that decreased methylation of PP2A catalytic C subunit caused by loss of LCMT-1 in prostate cancer abrogates the tumor suppressor activity of PP2A on AR/MED1-dependent gene expression, proposing decreased methyl-PP2A-C as a prognostic marker for prostate cancer progression." (PMID 37644036, 2023). "A proteomic profile study conducted on a transgenic prostate cancer mouse model exposed to methyl-selenium compounds revealed changes in proteins associated with prostate functional differentiation, androgen receptor signaling, protein folding, and endoplasmic reticulum stress responses." (PMID 37765058, 2023). "Also, mutations in the androgen receptor gene are uncommon in men with prostate cancer in the general population, so it would take a long time to get a large sample." (PMID 36824501, 2023). "However, in highly aggressive forms of prostate cancer, there is evidence of a loss of AR expression, and, therefore, these cancers become refractory to androgen suppression therapy." (PMID 36677878, 2023).
prostate carcinoma (continued). "Based on these results, we propose that longer polyQ sequences in AR may have a protective role against prostate cancer by enhancing self-association processes that reduce the AR transcriptional activity." (PMID 34986150, 2022). "Analysis of AR expression by IHC has also revealed that AR expression is reduced in prostate cancer-associated stroma relative to matched benign stroma, and negatively correlates with a high Gleason score, suggesting that stromal AR plays a tumor suppressive role." (PMID 36671452, 2022). "Moreover, studies have demonstrated that ANK3 is associated with prostate cancer and breast cancer by regulating the stability of AR." (PMID 35646694, 2022). "However, these small molecule inhibitors are ineffective against advanced prostate cancers with AR gene amplification, mutations, and alternate splicing." (PMID 35702041, 2022). "Loss of CAF-dependent AR activation may be responsible for castration-resistant prostate cancer progression." (PMID 35488263, 2022). "Besides analysis of CTCs, expression of androgen receptor splice variant 7 (AR-V7) in CTCs of prostate cancer patients has gained clinical interest for prediction of non-response to androgen receptor-targeted agents (ARTAs), i.e., abiraterone or enzalutamide." (PMID 35831403, 2022). "These combined observations suggested that the effect of cholesterol availability on prostate cancer cell proliferation could be linked to AR signaling via de novo steroidogenesis." (PMID 35033184, 2022). "Bruceantin could efficiently suppress tumor growth and metastasis of castration-resistant prostate cancer cells and overcome resistance caused by aberrant full-length androgen receptor (AR-FL)/AR-V7 signaling via targeting HSP90 expression." (PMID 35370639, 2022). "To investigate whether this association held true in human prostate cancer, we correlated a 200 gene signature of Tnf activity with AR signaling activity in the prostate cancer TCGA dataset." (PMID 36511483, 2022). "Additionally, β-catenin activation was found to dampen AR-mediated signaling in murine prostate cancer models and altered WNT pathway genes were associated with a decreased overall survival in mCRPC patients." (PMID 35740556, 2022). "Notably, CHD1 deletion is an early prostate cancer event, resulting in the loss of integrity of the AR cistrome." (PMID 36212399, 2022). "Furthermore, erastin, a classical inducer of ferroptosis, suppressed the transcriptional activities of both the full length and the splice variant of AR in castration resistant prostate cancer cells." (PMID 36077824, 2022). "In addition to the changes that occur during progression to metastatic disease, alterations to the AR cistrome also underly the development of therapeutic resistance in prostate cancer patients." (PMID 36212399, 2022). "Indeed, loss of AR signaling in prostate cancer lineage plasticity is strongly associated with extensive epigenetic reprograming." (PMID 35909568, 2022). "Advanced prostate cancer development is associated with androgen-independent AR signaling." (PMID 35454821, 2022). "Changes in AR expression or mutations are associated with prostate cancer." (PMID 35884607, 2022). "Early stage prostate cancers primarily express the full-length, 110 kDa version of the AR (also known as AR-FL), while AR-V7 and other AR variants have been detected within advanced prostate cancers and tumors that have developed resistance to androgen-deprivation therapy or antiandrogens." (PMID 36175875, 2022).
prostate carcinoma (continued). "These positive preliminary findings led to the FDA approval of rucaparib in May 2020 for BRCA1/2 mutated metastatic castration-resistant prostate cancer patients who progressed after one to two lines of AR-directed therapy and one taxane-based chemotherapy." (PMID 36010882, 2022). "Furthermore, our in vitro data demonstrate the association of IL8 and VEGF signaling with regulation of AR expression in hypoxic prostate cancer cells, consistent with these factors contributing to a target-associated resistance." (PMID 35302608, 2022). "Finally, Tnf signaling has previously been implicated as a pro-tumorigenic factor in AR low prostate cancer." (PMID 36511483, 2022). "Because of the selection process, the articles cover a diverse range of scientific contexts and include the human mitochondrial transcriptome, cancer-associated mutations of Dicer, regulation of the androgen receptor in prostate cancer, and mechanisms that establish microglial identity." (PMID 36355750, 2022). "Also, small molecules such as A4B17 have been implicated as promising AR-positive prostate cancer therapeutics by suppressing AR target genes involved in oxidative stress and metabolism." (PMID 36551308, 2022). "The initiation of prostate cancer has been long associated with DNA copy-number alterations, the loss of specific chromosomal regions and gene fusions, and driver mutations, especially those of the Androgen Receptor." (PMID 35205419, 2022). "Besides their role in therapeutic response, AR variants seem to play a key role in prostate cancer progression to a more aggressive stage." (PMID 34919781, 2022). "Mutations and amplifications of AR genes have been reported in prostate cancer and breast cancer." (PMID 36045397, 2022). "Considering this, we speculate that there is no literature concerning other tumors until now because other studies that analyzed this specific AR mutation focused primarily on breast and prostate cancer." (PMID 35053623, 2022). "In metastatic castration-resistant prostate cancer (mCRPC), an androgen-dependent type of prostate cancer, the cause of a failing response to androgen receptor (AR) inhibitors, enzalutamide and abiraterone, can be identified in the presence of androgen-receptor splice variants." (PMID 35582538, 2022). "The progression of prostate cancer is frequently accompanied by rising androgen receptor (AR) overexpression owing to the proliferation of luminal epithelial cells of the prostate caused by the accumulation of somatic mutations or AR amplification." (PMID 36209184, 2022). "Furthermore, it causes the suppression of androgen receptor expression and E2F-1, which is essential for the proliferation and viability of androgen-sensitive and androgen-independent prostate cancer cells." (PMID 35956766, 2022). "Pladienolide B treatment caused the regression of tumors bearing these androgen receptor variants, indicating that splicing inhibition could be exploited to target prostate cancers that have acquired resistance to standard therapies." (PMID 35406598, 2022). "Similarly, TLE5 suppressed prostate cancer metastasis by inhibiting AR and Notch signaling, and loss of TLE5 promoted tumor invasion and metastasis by increasing Snail and MMP9 expression." (PMID 36438567, 2022). "AR signaling mechanisms are the cause and treatment target for prostate cancers." (PMID 35884386, 2022). "Finally, we compared the two tools on an in-house dataset generated from the prostate cancer cell line 22Rv1, a well-studied cell line known for expressing different variants of the Androgen Receptor (AR) gene." (PMID 35164688, 2022). "Furthermore, surgical castration in prostate-specific Pten-deficient mice with prostate cancer led to a profound decrease of Gnmt mRNA levels, consistent with the repression of a bona fide AR target, Nkx3.1." (PMID 35197445, 2022).
prostate carcinoma (continued). "While evidence for angiogenic activity of AR in breast cancer is sparse, regulation of angiogenesis by AR in prostate cancer is implicated through interactions with epigenetic and transcriptional co-activation factors to regulate VEGF, and synergy between anti-androgenic and anti-VEGF therapies." (PMID 35203574, 2022). "Moreover, PBK was a downstream target of RORγ that exerted the cellular effects, indicating that PBK, RORγ, and AR were all associated with the growth and survival of aggressive prostate cancer." (PMID 35360870, 2022). "Moreover, we demonstrated that the androgen receptor mutation p.H875Y is not only relevant in prostate cancer but had a strong predictive value for colorectal, bladder, and breast cancer." (PMID 35053623, 2022). "The Jumonji C-containing histone lysine demethylase family 4 (KDM4) members, KDM4A‒KDM4C, serve as critical coactivators of AR to promote tumor growth in prostate cancer and are candidate therapeutic targets to overcome AR mutations/alterations-mediated resistance in CRPC." (PMID 35534851, 2022). "Increase in the level of AR-V7 with a truncated C-terminus, which could not be inhibited by the ligand-binding domain inhibitor, enzalutamide, caused continuous activation of AR signals, resulting in prostate cancer resistance to enzalutamide." (PMID 35504877, 2022). "Furthermore, many of the androgen-blocking agents (androgen deprivation therapy, androgen receptor blockers, and androgen metabolism inhibitors) used in the treatment of prostate cancer have been linked to augmented risk of IHD." (PMID 35435219, 2022). "Thus, the inhibition of autophagy due to both the DJ-1 and AR expression, in association with the growth of prostatic cancer cells, further strengthen the notion of a strict inter-regulation between DJ-1 and AR." (PMID 35563738, 2022). "AR is highly associated with prostate cancer with a score of 8.0, which is consistent with observations that it is often overexpressed in prostate cancer and mutations in the AR gene are present in a large population of castration-resistant prostate cancer patients." (PMID 35176995, 2022). "The GWAS data revealed that numerous SNPs near the AR locus are associated with prostate cancer." (PMID 35176995, 2022). "The PI3K and AR signaling pathways are directly linked to the development of prostate cancer." (PMID 36428613, 2022). "Indeed, for some particular gain-of-function AR-variants, authors discussed an increased dimerization effect through variants that promote tumor progression of prostate cancer." (PMID 34069457, 2021). "In another study, the combination of enzalutamide and navitoclax (ABT-263) increased sensitivity in both enzalutamide-sensitive and (primary and acquired) -resistant prostate cancer cells, with elevated proteasomal degradation of AR and AR splice variant 7 (AR-V7)." (PMID 35008216, 2021). "For example, the alternative RNA splicing of androgen-receptor (AR) splice variant 7 messenger RNA (AR-V7) may cause the resistance of AR pathway inhibitors, leading to the progression of prostate cancer." (PMID 34760337, 2021). "In prostate cancer, KLK3e, an androgen-induced eRNA, scaffolds the androgen receptor (AR)–associated protein complex could modulate chromosomal architecture and enhance AR-dependent KLK3 expression to promote prostate carcinogenesis." (PMID 33815468, 2021). "What is even more interesting is that prostate cancer patients with NMIBC undergoing androgen deprivation therapy or therapy with 5α-reductase inhibitors showed a similar effect of a reduced risk of recurrence when high AR protein expression was observed." (PMID 34209360, 2021).
prostate carcinoma (continued). "Both AR and ARv7 are associated with prostate cancer resistance and metastasis." (PMID 34206543, 2021). "Kohvakka and colleagues further demonstrated that the ERG- and AR-regulated lncRNA EPCART (ERG-positive PC-associated androgen responsive transcript) is functionally relevant for prostate cancer, as knockout of EPCART reduces migration and proliferation of LNCaP cells." (PMID 33634124, 2021). "In addition, platinum agents play a pivotal role in the treatment of prostate cancer that transitions to small-cell carcinoma or neuroendocrine tumors, thus acquiring resistance to hormone therapy and loss of the androgen receptor signaling pathway." (PMID 34948314, 2021). "Darolutamide causes the binding of AR to genome to be greatly reduced, which strongly inhibits the activation of normal enhancer and super-enhancers, and then hinders several downstream pathways which are very important for prostate cancer proliferation." (PMID 34976824, 2021). "Prostate cancer is almost uniformly dependent on androgens at its initial presentation, while the loss of AR expression during disease progression inevitably results in resistance to standard treatments that inhibit AR signaling." (PMID 33420371, 2021). "However, the mechanism involving androgen/androgen receptor signaling in cancer associated fibroblasts and consequences for prostate cancer progression still remains elusive." (PMID 33500395, 2021). "For example, interleukin (IL)-6 was found to induce the drug resistance of prostate cancer by activating the androgen receptor (AR), and IL-4 was found to be associated with the development of CRPC by regulating coactivators of AR such as The nuclear factor-kappaB (NF-κB)." (PMID 33673284, 2021). "Indeed, an AR variant, which is implicated in the development of castration-resistant prostate cancer, has recently been identified in bladder cancer." (PMID 34064926, 2021). "As a result, patients with prostate cancer that are treated with anti-AR therapy could be less susceptible to viral infection and the use of anti-AR compounds could be a therapeutic strategy and preventive option in these patients to avoid viral entry." (PMID 34442770, 2021). "Furthermore, a study in PTEN-deficient prostate cancer showed that AR and PI3K pathway activity were inversely related." (PMID 34680250, 2021). "Consistently, elevated risk of prostate cancer in certain populations may be associated with the difference in the distribution of prostate cancer risk associated genotypes i.e. AR, SRD5A2 and VDR." (PMID 34535145, 2021). "Interestingly, the PI3K and androgen receptor (AR) signaling pathways have an interactive feedback regulation in PTEN-deficient prostate cancer cells, and inhibition of either can activate this loop and thus limit the efficacy of single drug treatment." (PMID 33431808, 2021). "The increase of AR expression can reduce the content of prostate specific antigen in serum, and cause benign prostatic hyperplasia, and also has relation with the pathogenesis of prostate cancer." (PMID 34054930, 2021). "We performed a phase II study of a novel combination of AR-targeting agents in patients with clinically localized prostate cancer at high risk of disease recurrence and, despite biochemical responses in all patients, observed significant variability in measured tumor response." (PMID 34322653, 2021). "We then wonder to test the association between PRPF6 and AR in prostate cancer cells." (PMID 33390843, 2021).